RANGAP1 (Ran GTPase activating protein 1)
Diseases named in the same sentence as RANGAP1 in open-access papers (continued):
Sharing a sentence is not in itself a finding about the gene and the disease.
Sepsis (1 paper, 2025). Sepsis is defined as life-threatening organ dysfunction caused by a dysregulated host response to infection. "A total of six hub genes (RORA, L3MBTL2, PHC1, RPA1, CHD3, and RANGAP1) associated with SUMOylation was identified in sepsis in the current study." (PMID 40274894, 2025). "This study shows that hub genes (RORA, L3MBTL2, PHC1, RPA1, CHD3, and RANGAP1) may distinguish controls and diseases to facilitate diagnosis of sepsis." (PMID 40274894, 2025). "L3MBTL2, RPA1, and RANGAP1 have not been previously associated with sepsis, offering new avenues to explore their roles." (PMID 40274894, 2025). "Aflatoxin B1 was identified as a prospective therapeutic agent for sepsis based on CHD3, L3MBTL2, PHC1, RANGAP1, and RORA." (PMID 40274894, 2025).
tumor (16 papers, 2012 to 2024). "High expression of circ-RanGAP1 was associated with tumor volume, TNM stage, LNM, and poor prognosis in GC patients." (PMID 38094607, 2023). "To decipher the mechanism underlying RanGAP1-knockdown-induced cell-cycle arrest and tumor cell death in DLBCL lines, we tested the effects of RanGAP1 siRNA on the expression of Aurora kinases and TPX2." (PMID 24223200, 2013). "Tissue samples from 10 CRC patients demonstrated significantly elevated levels of RanGAP1 protein expression in tumor tissues compared to para-cancerous tissues." (PMID 38267624, 2024). "BRCA1 and HDAC1 exhibited significantly elevated expression in tumor samples, while RANGAP1 demonstrated significantly decreased expression in tumor samples." (PMID 38801243, 2024). "Using tumor tissues and public databases, we found that RanGAP1 was significantly upregulated in CRC tissues and was associated with poor prognosis of patients." (PMID 38267624, 2024). "High levels of circ-RanGAP1 were positively related with advanced tumor, node, metastasis (TNM) stages and high lymph node metastases." (PMID 37234708, 2023). "Another study showed that circ-RanGAP1 expression was significantly upregulated in tumor tissues and plasma exosomes of GC patients." (PMID 38094607, 2023). "In contrast, circ-RanGAP1 silencing attenuates GC cell invasion and migration, and represses tumor growth and metastasis in mice." (PMID 34607506, 2022). "In conclusion, using comparative proteomic analysis, we found that RanGAP1, a cell-cycle coordinator, was present in the tumor tissues and patient serum of high-grade BCL." (PMID 24223200, 2013). "In addition, the same conclusion was reached in the tissue microarray, and CRABP2 expression was also enhanced in CRC tumor tissues of patients with high RanGAP1 expression." (PMID 38267624, 2024). "Besides, cell function experiments and xenograft tumor models corroborated the function of RanGAP1 in CRC progression." (PMID 38267624, 2024). "Furthermore, we conducted an analysis of various stages of CRC and observed that non-metastatic CRC patients exhibited a significantly elevated mRNA level of RanGAP1 in tumor tissues based on the GSE68468 and GSE49355." (PMID 38267624, 2024). "Moreover, IHC indicated that the expression of Ki67 in RanGAP1 knockdown tumor tissues was observably lower." (PMID 38267624, 2024). "In xenograft tumor models, circ-RanGAP1 facilitated tumor growth and metastasis." (PMID 37234708, 2023). "Immunohistochemistry (IHC) of the excised tumor sections, which verified the correlation between proliferation and RanGAP1, indicated that the CRABP2 expression levels in RanGAP1 knockdown tumor tissues were observably lower." (PMID 38267624, 2024). "The potential oncogenic role of circ-RanGAP1 was assessed using CCK-8, colony formation, transwell assays in vitro, subcutaneous tumor mouse model, vein tail metastatic model, and orthotopically implanted intrahepatic HCC model in vivo." (PMID 36348379, 2022). "Initial findings indicated that RANGAP1, GOPC, NHLRC3, FZD6, and IDE were significantly correlated with stem cell indices and tumor microenvironment parameters." (PMID 35859893, 2022). "We next evaluated the correlation between RanGAP1 serum level and other clinicopathologic factors in DLBCL cases: tumor stage, treatment response, and patient survival." (PMID 24223200, 2013). "Because RanGAP1 is present in cytoplasm and perinucleus, and no secreted form is found, it is likely that the serum level arises from the death of tumor cells." (PMID 24223200, 2013).
cancer (14 papers, 2013 to 2024). A tumor composed of atypical neoplastic, often pleomorphic cells that invade other tissues. "Metastasis, migration and invasion associated cancer genes such as RanGAP1 (Ran-GTPase activating enzyme 1), Rho-like GTPase- Rac1, MMPs like MMP-9, MMP-14 and slug are found to be profoundly SUMOylated." (PMID 34715855, 2021). "To test if SUMO1-modified RanGAP1 is also evenly present between the two fractions in other types of cells, we fractionated four cancer cell lines (HeLa, BRL, 293T and U2OS) and two fibroblasts (GM03652 and NIH3T3) for immunoblot analysis." (PMID 26642330, 2015). "The current study showed that RanGAP1 is dysregulated in a variety of cancers." (PMID 35859893, 2022). "Since RanGAP1 was previously reported to be involved in the development of cancer, we question whether RanGAP1-derived circRNAs might also be involved in cancer progression." (PMID 36348379, 2022). "Furthermore, by analyzing the expression of two essential partners of Ran involved in GTP loading (RCC1) and hydrolysis (RanGAP1), we found that while the RCC1 gene is clearly overexpressed in 16 of 18 studied cancers, the dysregulation of RanGAP1 is cancer dependent." (PMID 32528950, 2020). "circ-RanGAP1 sponges miR-877-3p upregulate the VEGFA expression, thus promoting cancer cell aggressiveness in GC." (PMID 35685832, 2022). "Finally, by analyzing the change in gene expression between normal and transformed tissue in each cancer, we found that tumors are characterized by an imbalance of RCC1 and RanGAP1 in favor of Ran activation." (PMID 32528950, 2020). "Moreover, RanGAP1-specific siRNAs also inhibited the expression of Aurora kinases and TPX2, the key regulators of mitotic cell division, and clinical indicators of aggressive cancers." (PMID 24223200, 2013).
infection (7 papers, 2015 to 2025). The state of being infected such as from the introduction of a foreign agent such as serum, vaccine, antigenic substance or organism. "Consequently, an accumulation of potentially sumoylated RanGAP1 was observable in TPLs after infection and only in the presence of GP63, implying that GP63 may mediate the detachment of the sumoylated RanGAP1 from the NPC and Nup358 specifically." (PMID 25826301, 2015). "In contrast, RanGAP1, a cellular protein that is constitutively modified by both SUMO1 and SUMO3, remained unchanged during infection." (PMID 26814176, 2016). "Identification in our MS dataset of the sumoylated forms of PML and Sp100 as proteins whose abundance is significantly reduced during infection supported the validity of the experiment, as did the lack of change in sumoylated RanGAP1, which is not affected by HSV-1." (PMID 26200910, 2015). "The results showed that post-infection, SUMO2/3 partially co-localized with LaminB1, but not with RanGAP1 and RanBP2." (PMID 40521184, 2025). "We also confirmed our mass spectrometry data that RanGAP1 and PML are basally SUMOylated but largely do not change in modification status following IAV infection, whereas TRIM28 is highly deSUMOylated during infection." (PMID 26549460, 2015).
neurodegenerative disease (2 papers, 2021 to 2024). A disorder of the central nervous system characterized by gradual and progressive loss of neural tissue and neurologic function. "Disrupted distribution of RanGAP1 has been previously observed in neurodegenerative disease, and may be indicative of defects in NCT." (PMID 39452051, 2024). "Intriguingly, RanGAP1 gradient is disrupted in neurodegenerative diseases including ALS and HD." (PMID 34060470, 2021).
RANGAP1 also shares sentences with these, for which no sentence is quoted: amyotrophic lateral sclerosis (4 papers); frontotemporal dementia (3); diffuse large B-cell lymphoma (2); lung adenocarcinoma (2); osteosarcoma (2); viral infection (2); bladder cancer (1); brain injury (1); breast tumor (1); Chronic Myeloid Leukemia (1); COVID-19 (1); glioblastoma (1); leukemia (1); lung carcinoma (1); lymphoblastic lymphoma (1); lymphoplasmacytic lymphoma (1); mantle cell lymphoma (1); marginal zone lymphoma (1); mitochondrial disease (1); myelodysplastic syndrome (1); neurodevelopmental disorder (1); prostate adenocarcinoma (1); rectum adenocarcinoma (1); small lymphocytic lymphoma (1).